MIPEPP3 (mitochondrial intermediate peptidase pseudogene 3)
Gene: Transcribed unprocessed pseudogene on chromosome 13 (21,298,259 to 21,306,373, forward strand). Ensembl gene ENSG00000233325.
Diseases named in the same sentence as MIPEPP3 in open-access papers:
MIPEPP3 is named in the same sentence as 2 diseases in open-access papers, as found by Europe PMC text mining. Sharing a sentence is not in itself a finding about the gene and the disease.
MIPEPP3 shares sentences with these, for which no sentence is quoted: Anorexia (1 paper); Insulin resistance (1).